VDR (vitamin D receptor)
Diseases named in the same sentence as VDR in open-access papers (continued):
Sharing a sentence is not in itself a finding about the gene and the disease.
Anxiety (15 papers, 2014 to 2025). Intense feelings of nervousness, tension, or panic often arise in response to interpersonal stresses. "According to animal studies, there were motor impairments, increased grooming behavior, and anxiety-like behaviors among vitamin D-receptor-deficient mice." (PMID 35889792, 2022). "Reinforcing the anxiolytic role of VDR activation, a study conducted on VDR knockout mice found that the ablation of this receptor induced anxiety-like behavior." (PMID 39065743, 2024). "In an experimental model of contextual fear conditioning in rats used to understand fear and anxiety in humans, VDR was upregulated in the prefrontal region." (PMID 39062692, 2024). "For example, “Prostanoid Biosynthesis” and “OX40 Signaling Pathway” were exclusively enriched in innate anxiety while “Calcium-induced T Lymphocyte Apoptosis” and “VDR/RXR activation” were only enriched in stress-induced anxiety." (PMID 37260777, 2023). "At the end of the study, five behavioral tests were conducted to assess cognitive functions, motor activity, and anxiety-related behaviors, and hippocampal tissues were analyzed for tau pathology, neuroinflammation, expression of VDR, and neurodegeneration-related markers." (PMID 40542117, 2025). "Neurons and glial cells in different areas of the prefrontal cortex and hippocampus system expression of VDR and vitamin D metabolism enzymes, suggesting that vitamin D may play a role in anxiety." (PMID 38549749, 2024). "Previous studies have found that VDR knock-out mice showed increased anxiety symptoms." (PMID 28054941, 2017). "While the mechanism by which VitD3 could play a role in anxiety is unknown, neurons and glial cells that express VDR and VitD3-metabolizing enzymes are present in several different regions of the brain that control emotion, including the cortex, cerebellum, and limbic system." (PMID 38684734, 2024). "Animal experiments have demonstrated that mice lacking the VDR gene showed an increase in anxiety-like behavior." (PMID 28054941, 2017). "While some studies reported no observed impairments in working memory or anxiety in the VDR-KO model mouse, others showed anxiety-like behavior and behavioral impairment." (PMID 25344727, 2014).
heart failure (15 papers, 2013 to 2025). Inability of the heart to pump blood at an adequate rate to meet tissue metabolic requirements. "Another study has recentlyexamined the relationship between VDR genotypes, plasma concentrations of vitaminD metabolites and risk of heart failure and metabolic disorders (includingobesity)." (PMID 39076268, 2023). "This study is the first to our knowledge to reveal the genetic variation and allele frequencies correlations of VDR genetic polymorphisms with heart failure and MACE among ACS patients in the Egyptian population." (PMID 37259407, 2023). "Earlier studies examining the effect of VDR loss on MI-induced heart failure progression reported higher mortality and accelerated cardiac pathology in hypocalcaemic VDR mutant mice on a normal diet, 4 weeks post-MI." (PMID 30273386, 2018). "Our finding that mice with a cardiomyocyte-specific deletion of the VDR exhibited more pronounced LV functional impairment after TAC than controls aligns with a post-hoc analysis of the EVITA (Effect of VITamin D on All-cause mortality in heart failure) trial." (PMID 38892126, 2024). "Moreover, we identified the genetic variants of vitamin D receptor (VDR) gene polymorphisms are linked to cardiac failure and MACE in ACS patients." (PMID 37259407, 2023). "In a recent Chinese study, the significantly lower levels of vitamin D and altered presence of VDR variants -an increased prevalence of heterozygous and minor alleles for FokI (f minor allele) and TaqI (t minor allele) variants, were found in patients with heart failure." (PMID 38243935, 2024). "However, whether activation of vitamin D receptor (VDR) can attenuate heart failure and underlying metabolic phenotype requires investigation." (PMID 35726330, 2022). "Bile acids may also impact cardiomyocytes via TGR5 and the vitamin-D receptor, explaining their cardiotoxic (mainly hydrophobic bile acids) and cardioprotective (mainly hydrophilic bile acids) effects in heart failure." (PMID 41325840, 2025). "With respect to inflammatory processes, areduction in VDR expression, as well as increases in Th2 cells and Th2 cytokineproduction in myocarditis at end stage heart failure has been reported;reconstitution of the vitamin D receptor in CD4+ T cells attenuated Th2-mediatedinflammation." (PMID 39076268, 2023). "We next asked the question whether the MI-induced functional impairment and heart failure progression differs between normocalcaemic VDR mutants on rescue diet and WT mice." (PMID 30273386, 2018). "Vitamin D receptor (VDR) is expressed in cardiovascular system and clinical evidence have reported that vitamin D exerts a beneficial role in cardiac remodeling and heart failure survival." (PMID 36575556, 2022).
lymphoma (15 papers, 1993 to 2025). A malignant (clonal) proliferation of B- lymphocytes or T- lymphocytes which involves the lymph nodes, bone marrow and/or extranodal sites. "We found four loci located in the Vitamin D Receptor gene, which encodes a putative key regulator of gene expression in lymphoma." (PMID 38144469, 2023). "Vitamin D and its analogues showed an antiproliferative effect on lymphoma cell lines and diminished the expression of the VDR." (PMID 36771203, 2023). "At the same time, it was possible to induce VDR expression in lymphocytes in response to mitogen or specific antigens, while VDR expression was detected in cancer lymphoma cells." (PMID 32197412, 2020). "The role of VDR in carcinogenesis and outcomes of hematopoietic malignancies remains poorly studied, though high expression of VDR has been described in several lymphoid cancers." (PMID 32357551, 2020). "Vitamin D and its metabolites have been shown to have an antiproliferative effect on lymphoma cell lines and to attenuate their vitamin D receptor (VDR) expression." (PMID 23556533, 2013). "WES revealed significantly mutated genes, including several known (NCF1, MMP9, and VDR) and possibly other candidate (CNN2, MUC4, MTSS2, KMT2C, HAVCR2, and TCF19) genes, most of which were associated with the physiological activation of lymphoma cells." (PMID 41296384, 2025). "Expression of the VDR was low in each cell line and in the low grade lymphoma tumour samples." (PMID 8398690, 1993). "For Tru91 polymorphism in the VDR gene, the homozygous genotype GG was the most common in cases of CML and CLL, and which had no impact on lymphoma (HL and NHL) illness." (PMID 38125732, 2024).
squamous cell carcinoma (15 papers, 2013 to 2025). A carcinoma arising from squamous epithelial cells. "Here, we showed the deletion of either VDR or PDIA3 decreased baseline calcium levels in squamous cell carcinoma A431 cells and further impaired calcium influx induced by 1,25(OH)2D3." (PMID 38201216, 2023). "The authors found that treatment of murine squamous cell carcinoma cells with dexamethasone in combination with 1,25-dihydroxyvitamin D3 lead to the upregulation of VDR." (PMID 35058935, 2021). "Downregulation of VDR expression results in increased cell migration of A431 epidermoid carcinoma cells, which can be rescued by ΔNp63α or VDR." (PMID 23710361, 2013). "At first sight, the findings of photoprotective effects of CaSR knockdown or pharmacologic inhibition in human keratinocytes are inconsistent with reports that mice with epidermal double knockout of the VDR and CaSR spontaneously develop squamous cell carcinomas." (PMID 35288938, 2022). "The deletion of PDIA3 not only affected membrane signaling but also genomic responses to vitamin D. Moreover, it seems that both VDR and PDIA3 are required for the regulation of calcium signaling induced by 1,25(OH)2D3 in A431 squamous cell carcinoma." (PMID 38201216, 2023). "In conclusion, this study demonstrated that both VDR and PDIA3 are needed to regulate membrane response to active forms of vitamin D in A431 squamous cell carcinoma, possibly through CAMKIIα and impaired calcium influx, respectively." (PMID 38201216, 2023). "Moreover, it seems that VDR and PDIA3 are required for the regulation of calcium influx induced by 1,25(OH)2D3 in squamous cell carcinoma." (PMID 38201216, 2023). "The best hybrid, 1173, is a full VDR agonist, as assessed by several criteria, and an efficacious antiproliferative agent against both 1,25D-sensitive (SCC25, AT84) and 1α,25(OH)2D3-resistant (SCC4) squamous carcinoma cell lines." (PMID 36432615, 2022). "As VDR ablation sensitizes skin to chemically induced squamous cell carcinoma these data suggest that lack of VDR specifically in the transitional epithelia/epidermis of the anus causes susceptibility to chemical carcinogen induced tumorigenesis." (PMID 27768599, 2016). "Finally, analysis of samples from patients with squamous cell carcinoma (SCC), basal cell carcinoma and precursors to invasive SCC demonstrated a significant correlation between p63 and VDR levels when compared with healthy normal skin control samples." (PMID 26068789, 2015). "Since ΔNp63α has been shown to inhibit cell invasion via regulation of VDR, we wanted to determine whether dietary Vitamin D3 protected against UVB induced tumor formation in SKH-1 mice, a model for squamous cell carcinoma development." (PMID 25191969, 2014). "Here, the role of VDR and PDIA3 proteins in membrane response to 1,25(OH)2D3 and calcium signaling was investigated in squamous cell carcinoma A431 cell line with or without the deletion of VDR and PDIA3 genes." (PMID 38201216, 2023). "In our latest studies, we investigated the impact of deletion of either VDR or PDIA3 on gene expression profile and non-genomic effects of 1,25(OH)2D3 in A431 squamous cell carcinoma, showing that PDIA3 is involved in genomic responses to 1,25(OH)2D3." (PMID 38201216, 2023).
bladder cancer (14 papers, 2013 to 2025). "On the other hand, high VDR expression has been associated with improved prognosis of patients with lung, prostate, pancreatic, colorectal, and bladder cancers." (PMID 36291915, 2022). "Increased risk for bladder cancers seems to be associated with Fok-I VDR polymorphism." (PMID 26501255, 2015). "Therefore, we suggest that crossing of the deeper layers of the muscularis propria by bladder cancer cells and acquisition of metastatic potential are linked to a loss or significant reduction of VDR expression." (PMID 26501255, 2015). "The studies of VDR polymorphism in urinary bladder cancers are sparse." (PMID 26501255, 2015). "All of the four bladder cancer cells express endogenous and inducible vitamin D receptor (VDR) as examined by immunoblot analysis." (PMID 28947955, 2017). "The highest VDR immunostaining was found in normal epithelium and was significantly lower in bladder cancer cells (p < 0.001 with Mann–Whitney U test)." (PMID 26501255, 2015). "Since vitamin D is a positive regulator of VDR expression, we cannot exclude the possibility that the VDR levels in bladder cancer cells are related to and/or regulated by the local and systemic vitamin D levels." (PMID 26501255, 2015). "In the future we plan to perform prospective study on vitamin D serum level, VDR polymorphisms and epigenetic regulation of VDR and CYP27B1 expression in in patients with bladder cancer." (PMID 26501255, 2015). "Multivariate-adjusted RRs with 95% CIs of death in relation to nuclear and cytoplasmic VDR immunostaining in urinary bladder cancers." (PMID 26501255, 2015). "Increased NCOR1 and NCOR2/SMRT expression occurs also in breast and bladder cancer and suppressed the responsiveness of nuclear receptors that exert mitotic restraint, such as VDR and PPARα,γ." (PMID 23098689, 2013). "Moreover, nuclear and cytoplasmatic VDR staining was observed in endometrioid cancer cells, whereas in urinary bladder carcinoma, VDR staining was cytoplasmatic and membranous." (PMID 40186735, 2025). "This hypothesis is supported by the observation of lower VDR levels in metastasizing bladder cancers." (PMID 26501255, 2015). "We also suggest that vitamin D-based therapies may represent an adjuvant strategy in treatment for bladder cancers expressing VDR." (PMID 26501255, 2015). "The differences in VDR expression in bladder cancer suggest that vitamin D-based therapies may represent a promising previously unexplored strategies of bladder cancer treatment." (PMID 26501255, 2015). "Furthermore, vitamin D was shown to prevent bladder tumorigenesis in rats treated with a carcinogen N-methylnitrosourea as well as to inhibit cell growth of VDR-positive bladder cancer lines." (PMID 26770009, 2015). "Thus, the lower VDR expression could reflect vitamin D insufficiency, which led to poor outcomes in these bladder cancer patients." (PMID 26501255, 2015). "Thus routine anticancer therapy with systemic application of vitamin D3 or transurethral application of active forms of vitamin D3 could be an efficient mode of action resulting in the longer survival of VDR-positive bladder cancer patients." (PMID 26501255, 2015). "We analyzed VDR and CYP27B1 in samples of tumor and normal tissues obtained from 71 urinary bladder cancer patients." (PMID 26501255, 2015). "Both the nuclear and cytoplasmic VDR immunoreactivities were significantly lower in primary bladder cancers that metastasized in comparison to primary non-metastasizing tumors." (PMID 26501255, 2015). "In the tested bladder cancer samples, VDR expression was not related to several defined histological markers of malignancy such as mitotic activity or histological grade, whereas the presence of VDR in bladder cancer cells was related to longer OS." (PMID 26501255, 2015). "Both cytoplasmic and nuclear VDR staining was significantly higher in bladder cancers that did not develop metastasis compared with those that metastasized." (PMID 26501255, 2015).
bladder cancer (continued). "There was a strong relationship between VDR expression and the biology and stage of bladder cancers, with a lack of such correlation for CYP27B1." (PMID 26501255, 2015). "The aim of the present research was to examine whether the expression of the VDR and CYP27B1 in bladder cancer was related to the prognostic markers and disease outcome." (PMID 26501255, 2015). "Summary of the results related to VDR and CYP27B1 expression in urinary bladder cancers." (PMID 26501255, 2015). "However, our analysis of VDR and CYP27B1 immunostaining in urinary bladder cancers is very comprehensive and clinically significant, because of inclusion of data on overall survival time, which also correlated with histological parameters." (PMID 26501255, 2015). "This correlation suggests that disturbances of VDR expression might affect bladder cancer cell differentiation and that a lack of or decrease in VDR expression may make these cells unresponsive to the antitumorigenic action of active forms of vitamin D." (PMID 26501255, 2015). "The expression of both the VDR and CYP27B1 has been found in many normal and cancer tissues, but there is a lack of information about its expression in human bladder cancers." (PMID 26501255, 2015).
oral cancer (14 papers, 2015 to 2025). "This review assesses and integrates research concerning the influence of VDR gene variants on the development of tobacco-related oral cancer, emphasizing genetic underpinnings of individual vulnerability and possible tailored preventative approaches." (PMID 40356850, 2025). "Understanding the role of genetic predisposition, particularly VDR polymorphisms, alongside extrinsic factors like tobacco smoking, is crucial given the multifactorial origins of oral cancer." (PMID 40356850, 2025). "This review indicates a potential correlation between various VDR gene variations such as FokI, BsmI, TaqI, and ApaI and an increased risk of oral cancer linked to tobacco use." (PMID 40356850, 2025). "A meta-analysis that searched MEDLINE and ResearchGate up to June 2017 identified 12 articles covering 26 studies on VDR polymorphisms (FokI, ApaI, TaqI, BsmI) related to tobacco-associated lung, neck, head, esophageal, and oral cancers." (PMID 40356850, 2025). "While this review offers valuable insights into the role of VDR polymorphisms in tobacco-related oral cancer, it is essential to recognize its limitations." (PMID 40356850, 2025). "This study finds that VDR (Taq1) polymorphism is correlated with susceptibility to oral cancer and pre-cancerous conditions in the North Indian population." (PMID 40356850, 2025). "In 110 patients with oral neoplastic lesions, premalignant lesions, and oral cancer, VDR expression was increased, while insufficient or deficient blood levels of this micronutrient are prevalent in India41." (PMID 32686744, 2020). "This study aims to present evidence supporting the hypothesis that individuals with high-risk VDR genotypes may experience a synergistic effect from tobacco smoking, increasing their likelihood of developing oral cancer." (PMID 40356850, 2025). "Genotyping for VDR polymorphisms could help identify individuals at increased risk for oral cancer, particularly in populations with high tobacco use." (PMID 40356850, 2025). "This research underscores the role of VDR gene variants in tobacco-related oral cancer." (PMID 40356850, 2025). "VDR gene polymorphisms might also be a part of future preventive and therapeutic strategies against oral cancer." (PMID 37242229, 2023). "In addition, among Indian cancer patients with inadequate or deficient blood levels of vitamin D, an increase in VDR expression was seen in 110 cases of oral neoplasms, premalignant nodules, and oral cancer." (PMID 37259407, 2023). "Because OLP is considered a potential precancerous lesion, single nucleotide polymorphisms (SNPs) in VDR or vitamin D pathway genes may also play important roles in oral cancer." (PMID 33897222, 2020). "For example, VDR FokI gene polymorphism was related to an unfavorable survival rate in oral cancer." (PMID 31216637, 2019). "Consequently, individuals with certain VDR polymorphisms may have reduced capacity to mitigate the inflammatory and oxidative damage caused by tobacco, potentially elevating their risk for oral cancer." (PMID 40356850, 2025). "Finally, specific polymorphisms of the VDR gene have been directly linked to oral cancer and could represent a pathway for developing new preventive and therapeutic interventions." (PMID 37242229, 2023). "The potential link between VDR gene variations and tobacco-related oral cancer has significant implications for clinical practice and public health." (PMID 40356850, 2025). "The association between Vitamin D Receptor (VDR) polymorphisms and different cancers has attracted growing attention; nonetheless, the function of these genetic variants in tobacco-related oral cancer remains little comprehended." (PMID 40356850, 2025). "The findings of this research highlight the potential significance of VDR gene variations in determining the likelihood of developing oral cancer as a result of tobacco use." (PMID 40356850, 2025).